IL17F (interleukin 17F)
Diseases named in the same sentence as IL17F in open-access papers (continued):
Sharing a sentence is not in itself a finding about the gene and the disease.
rheumatoid arthritis (41 papers, 2008 to 2026). A chronic, systemic autoimmune disorder characterized by inflammation in the synovial membranes and articular surfaces. "Gene polymorphisms in cytokines IL-17F (7488 A/G) and IL-12B (1188 A/C) can predict disease susceptibility and severity in Bangladeshi rheumatoid arthritis patients." (PMID 38344692, 2024). "The study concluded that the IL-17F (7488 A/G) polymorphism with GG genotype and G alleles is related to the severity and susceptibility to rheumatoid arthritis." (PMID 38344692, 2024). "The expression of both IL-17A and IL-17F is detectable within synovial tissue, and their presence has been implicated in the pathogenesis of rheumatoid arthritis (R." (PMID 37751416, 2023). "A meta-analysis on rheumatoid arthritis conducted in 2017 and a meta-analysis on various cancers in 2016 reported the IL17F variant to be a risk locus." (PMID 31831764, 2019). "The aim of this study was to examine the association between the polymorphisms in IL17A and IL17F genes and rheumatoid arthritis." (PMID 27169372, 2016). "Systemically, IL-17A and IL-17F have been reported to play a pathogenic role in certain autoimmune diseases, including multiple sclerosis and rheumatoid arthritis." (PMID 23956759, 2013). "To date, there are some studies related to IL-17A G-197A (rs227593) and IL-17F A7488G (His161Arg, rs763780) gene SNPs and risk of tuberculosis (TB), gastric cancer, rheumatoid arthritis (RA), intestinal bowel disease (IBD), Crohn's disease (CD), ulcerative colitis (UC), and others." (PMID 25431761, 2014). "IL-17A and IL-17F genes are mapped on the same chromosome at position 6p12, and the polymorphisms of IL-17A G197A (rs2275913) and IL-17F C7488T (rs763780) have recently been associated with higher susceptibility to rheumatoid arthritis and ulcerative colitis." (PMID 23304063, 2012). "The IL-17 family of cytokines, which includes the T cell–derived proinflammatory cytokines IL-17A and IL-17F, has been implicated in the pathogenesis of rheumatoid arthritis (RA) and, more recently, juvenile idiopathic arthritis (JIA)." (PMID 18311821, 2008). "Disease activity and severity measures of rheumatoid arthritis were substantially (P < 0.05) higher in the IL-17F (7488 A/G) GG genotype than in the AA genotype and in the IL-12B (1188 A/C) AC and CC genotypes than in the AA genotype." (PMID 38344692, 2024). "Interleukin-17F (IL-17F), considered a pro-inflammatory cytokine, has been shown to contribute to skeletal tissue degradation and hence chronic inflammation in rheumatoid arthritis (RA)." (PMID 37751416, 2023). "Several inflammatory diseases, including rheumatoid arthritis, inflammatory bowel disease, asthma, Graves’ disease, ulcerative colitis, and cancer, have identified IL-17F as a promising candidate gene." (PMID 37751416, 2023). "Overproduced cytokines of Th17 cells, especially IL-17A, IL-17F, IL-21, and IL-22, play a role in osteodestructive diseases such as rheumatoid arthritis (RA) and PD." (PMID 36983201, 2023). "Soluble IL-17RC protein, which is a common receptor subunit for IL-17 and IL-17F, has been reported to exist and applied in rheumatoid arthritis via intraperitoneal injection." (PMID 34180764, 2021). "Treatment of synoviocytes from patients with rheumatoid arthritis with either recombinant IL-17A or IL-17F, in the presence of TNF, has been shown to induce a qualitatively similar gene signature." (PMID 32973785, 2020). "The levels of IL-17A, IL-17F, IL-17RA, and IL-17RC are also high in the sera and inflamed synovium of patients with rheumatoid arthritis." (PMID 23956759, 2013). "Others have shown that IL17A or IL17F gene polymorphisms play a role in Rheumatoid Arthritis (RA) and asthma, but there are fewer reports on associations of the IL17A gene polymorphisms with UC; particularly, there are no reports about IL17A gene polymorphism in Chinese UC patients." (PMID 22984500, 2012).
rheumatoid arthritis (continued). "The objective of the present study was to evaluate the effects of Enalapril, Losartan and Valsartan on the production of IL-2, IL-10, IL-6, TNF, IFN-γ, IL-17A, IL-17F and IL-22 cytokines in PBMCs of patients with rheumatoid arthritis and evaluate this modulation with disease activity." (PMID 30288187, 2018). "Top canonical pathways in diabetic gastroparesis included genes involved with macrophages, fibroblasts and endothelial cells in rheumatoid arthritis, osteoarthritis pathway and differential regulation of cytokine production in macrophages and T helper cells by IL-17A and IL-17F." (PMID 30086735, 2018). "Some researchers have recently shown that IL-17A and/or IL-17F are responsible for development of inflammation in many disorders, especially in autoimmune diseases like rheumatoid arthritis (RA), psoriasis, juvenile idiopathic arthritis (JIA), Crohn’s disease and many others." (PMID 26062902, 2015). "In addition, it is quite clear that VDR ligands directly target also Th17 cell subtype, as shown by the reduction of Th17 cytokines, such as IL-17A, IL-17F, and IL-22 by memory T cells in patients with early rheumatoid arthritis (RA)." (PMID 24895631, 2014). "The drug significantly regulates the cytokines IFN-γ, IL6, IL17F, and IL22 s in peripheral blood mononuclear cells of rheumatoid arthritis subjects." (PMID 34064039, 2021). "In rheumatoid arthritis (RA), high protein levels of IL-23 and IL-17F were detected in the synovial fluid of patients displaying ectopic lymphoid follicles, and a positive correlation was observed between CD21L mRNA (as a TLS marker) and IL-23 but also IL-17F, IL-21, and IL-22 mRNAs." (PMID 27752258, 2016). "Therefore, IL-17A and IL-17F may both participate in the pathogenesis of rheumatoid arthritis." (PMID 22028860, 2011). "IL-17A and/or IL-17F play important roles in many autoimmune diseases, e.g., leading to aggravation of such conditions as experimental autoimmune encephalomyelitis (EAE), psoriasis, rheumatoid arthritis (RA), and Crohn’s disease." (PMID 29892286, 2018).
chronic mucocutaneous candidiasis (28 papers, 2010 to 2025). "IL-17F plays a significant role in inflammatory responses and offers protection at barrier surfaces, as demonstrated by the increased susceptibility to chronic mucocutaneous candidiasis in individuals with an autosomal dominant deficiency of IL-17F." (PMID 40563358, 2025). "IL-17F plays an important role in inflammatory responses and protection at barrier surfaces, as shown by an intensified susceptibility to chronic mucocutaneous candidiasis in humans with an IL-17F deficiency." (PMID 36449073, 2023). "Mutations in IL-17RA and IL-17F have been linked to chronic mucocutaneous candidiasis disease and predisposition to Staphylococcus aureus infection." (PMID 37115755, 2023). "In fact, genetic deficiency of IL17RA or IL17F is associated with chronic mucocutaneous candidiasis and secukinumab -induced IL17F inhibition results in increased incidence of Candida spp." (PMID 34079536, 2021). "Chronic mucocutaneous candidiasis with autosomal recessive IL-17RC deficiency leads to impaired cellular responses to IL-17A and IL-17F." (PMID 34071562, 2021). "In humans, rare mutations in the genes encoding IL-17F, IL-17RA, IL-17RC, RORc and Act1 are strongly associated with chronic mucocutaneous candidiasis (CMC)." (PMID 26274976, 2015). "In fact, it has been demonstrated that chronic mucocutaneous candidiasis (CMC) occurs in patients with autosomal recessive IL‐17RA deficiency and autosomal dominant IL‐17F deficiency." (PMID 39634792, 2024). "Autoantibodies against IL-22 and IL-17F seem to be correlated with chronic mucocutaneous candidiasis as previously reported, suggesting that Th17 cytokines are central in human epithelial immunity against candida infection." (PMID 38605470, 2025). "Autoimmune polyendocrinopathy-candidiasis-ectodermal dystrophy (APECED) with chronic mucocutaneous candidiasis shows neutralizing autoantibodies against Th17 cytokines and significant defects in IL-17F and IL-22 production." (PMID 34071562, 2021). "IL-22 along with IL-17F is a vital natural defender against Chronic Mucocutaneous Candidiasis (CMC)." (PMID 33042126, 2020). "Chronic mucocutaneous candidiasis (CMC) is associated with anti-interleukin (IL)-17A, anti-IL-17F, or anti-IL-22 autoantibodies." (PMID 31892200, 2019). "Chronic mucocutaneous candidiasis (CMC) is a recurrent infection of skin, mucosae and nails (onychomycosis), frequently seen in individuals with mutations that affect Th17 cells, the cytokines IL-17A and IL-17F, or their receptor IL-17RA." (PMID 25849644, 2015). "Mutations in IL17F, IL17R and DECTIN1 in patients with chronic mucocutaneous candidiasis, as well as neutralizing autoantibodies against IL-17 and IL-22 in patients with autoimmune polyendocrinopathy-candidiasis-ectodermal dystrophy, directly impair IL-17 and IL-22 immunity." (PMID 23853597, 2013). "Interestingly, neutralizing autoantibodies against Th17 cell cytokines IL-17A, IL-17F, and IL-22 have been reported in chronic mucocutaneous candidiasis (CMC) patients with autoimmune polyendocrinopathy syndrome-1 (APS-1) or thymoma." (PMID 21079687, 2010). "In humans, failure to generate effective Th17 responses (as a result of a range of mutations in, for example, IL-17RA, IL-17F, STAT1 genes) can result in chronic mucocutaneous candidiasis (CMC)." (PMID 26124761, 2015). "Chronic mucocutaneous candidiasis (CMC) has been observed in individuals with anti-IL-17A, anti-IL-17F, and anti-IL-22 autoantibodies, resulting from these autoantibodies blocking the Th-17 immunity." (PMID 35003106, 2021). "Both autoimmune polyendocrinopathy‐candidiasis‐ectodermal dystrophy (APECED) and the rare thymoma patients with chronic mucocutaneous candidiasis (CMC) have neutralizing autoantibodies to Th17 cytokines and significant defects in production of IL‐22 and IL‐17F by their T cells." (PMID 27957331, 2016).
chronic mucocutaneous candidiasis (continued). "Interestingly, patients with chronic mucocutaneous candidiasis were shown to exhibit defects in IL-17F and IL-17RA but not IL-17A, indicating that IL-17F has a defined protective role against this infection." (PMID 29048384, 2017).
Autoimmunity (25 papers, 2011 to 2024). The occurrence of an immune reaction against the organism's own cells or tissues. "This miRNA cluster is connected to the pathogenicity of Th17 due to pathogenic cytokine production, including IL-17A and IL-17F, and mediates autoimmunity by repression of FOXO1 and induction of IL-1R1 expression." (PMID 37834058, 2023). "The up- or down-regulation of IL-17 genes (IL-17A, IL-17B, IL-17D, and IL-17F) resulted in decreased expression of many cytokines and chemokines, which are associated with autoimmunity and immune cell functions." (PMID 35466218, 2022). "To date, IL-17A and IL-17F are the most studied, although the latter is less implicated in autoimmunity, partly due to significantly reduced signaling triggered by IL-17F." (PMID 28149838, 2017). "Th17 cell is one lineage of T helper cells originated from naive CD4+ T cells, and secretes pro-inflammation cytokines, such as IL-17A and IL-17F, participating in inflammatory response, autoimmunity, and transplant rejection." (PMID 36792629, 2023). "IL-17A is involved in inflammation and autoimmunity, while IL-17F is predominantly involved in mucosal defense mechanisms." (PMID 36396672, 2022). "Nevertheless, in regard to autoimmunity and chronic inflammatory diseases, IL-17A, IL-17C and IL-17F act as the key mediators in manipulating the pathway cellular machinery." (PMID 35203707, 2022). "Biological features of the two cytokines appear to be distinct, with IL-17F being best characterized as a mediator of mucosal immunity and IL-17A as an important mediator of inflammatory reactions and autoimmunity." (PMID 36366333, 2022). "IL-17A and IL-17F are eponymous cytokines of the Th17 cell lineage, and IL-17A is believed to have a greater influence on driving autoimmunity than IL-17F because of its more potent signaling ability." (PMID 36569854, 2022). "Herein, the discussion is focused on IL-17A, IL-17C and IL-17F, since these families mediate autoimmunity the best, albeit in the presence of other additional families." (PMID 35203707, 2022). "As the subpopulation of T helper cells, Th17 cells produce IL-17 A/IL-17F and play a pivotal role in inflammation, autoimmunity, and host defense against extracellular pathogens." (PMID 34194525, 2021). "This is in keeping with other studies demonstrating overlapping functions of IL-17F and IL-17A in models of autoimmunity and pathogen clearance." (PMID 32753746, 2020). "Today, six IL-17 homologous molecules are known (IL-17A-F) and most of the research is focusing on IL-17A and IL-17F which were shown to be important for autoimmunity and inflammation." (PMID 29931394, 2018). "Due to its lower affinity, IL-17F seems to be less proinflammatory and IL-17A is more critical than IL-17F in mediating inflammation and autoimmunity, such as in experimental autoimmune encephalomyelitis (EAE)." (PMID 28210632, 2017). "IL17A and IL17F are mainly produced by a subset of CD4+ T cells (Th17 cells) and have been linked to a variety of inflammatory and autoimmune conditions." (PMID 22216338, 2011). "As revealed by evidencing studies, NLRC3 increases many genes related to the activation of Th1/Th17/T cells, such as Ifng, Tnf, Il17f, Il17a, and Tbx21; also, study reveals that Nlrc3 expression in T cells inhibits autoimmunity as well as CD4+ T cell responses specific for virus." (PMID 38436712, 2024). "Dysregulated IL-17A and IL-17F contribute to chronic inflammation and autoimmunity." (PMID 37834058, 2023). "Her daughter only had autoantibodies against IL-17F as a sign of autoimmunity." (PMID 37235056, 2023). "Furthermore, IL-17A induced inflammatory cytokines more strongly than IL-17F in the autoimmunity, but IL-17F has more critical roles than IL-17A in protecting colonic epithelial cells against the invasion of bacteria." (PMID 34267744, 2021).
Autoimmunity (continued). "Although mammalian IL-17A and IL-17F play important and similar roles in inflammation, IL-17A can induce inflammatory cytokines more strongly than IL-17F in the autoimmunity, and IL-17F plays a more critical role than IL-17A in protecting colonic epithelial cells from bacterial invasion." (PMID 34267744, 2021). "IL-17A and IL-17F which are highly homologous members of the IL-17 protein family and bind the same receptor complex consisting of IL-17RA and IL-17RC were often described as pro-inflammatory cytokines with redundant role in inflammation and autoimmunity." (PMID 21858022, 2011). "IL-17A and IL-17F are the most studied proteins of the IL-17 cytokine family, with both proteins pro-inflammatory under most of the conditions studied and may participate in driving autoimmunity." (PMID 30161145, 2018). "Of the two highly homologous IL-17 family members, IL-17A and IL17F, we focused on IL-17A, because, unlike IL-17F, IL-17A appears to mediate autoimmunity." (PMID 27095999, 2015). "In addition, similar to other models of autoimmunity, depletion of IL17A and, more importantly, IL17RC may reduce the severity of eye disease after HSV-1 infection by affecting both IL17A and IL17F functions." (PMID 32516406, 2020).
COVID-19 (22 papers, 2020 to 2025). A disease caused by infection with severe acute respiratory syndrome coronavirus 2. "It is desirable to examine the effectiveness of IL17F as a diagnostic marker by collecting samples from COVID-19 patients upon admission in future." (PMID 35264675, 2022). "The eQTL data using the Genotype-Tissue Expression (GTEx) database for three SNPs that met the genome-wide significance level in the IL17A/IL17F gene region showed that IL17F mRNA expression levels were significantly reduced by carrying the risk allele associated with COVID-19 severity." (PMID 35264675, 2022). "Overall, these results have identified an association between two cytokines of the IL-17 family (IL-17D and IL-17F) with COVID-19 and disease severity." (PMID 39493750, 2024). "Using high-throughput multiplexed proteomics, we profiled 1,500 protein biomarkers and identified 148 unique biomarkers in COVID-19 patients with IMIDs, including elevated inflammatory cytokines (e.g., IL-17F) and bone resorption markers." (PMID 39704167, 2024). "It was shown that the expression of Th17 cell-associated genes (RORC, IL17A, IL17F, and CCR6) was downmodulated in peripheral blood CD4+ T cells in COVID-19 patients." (PMID 37626620, 2023). "Although no significant genome-wide association was detected in the Japanese GWAS, an integrated analysis with the international meta-GWAS identified for the first time the involvement of the IL17A/IL17F gene in the severity of COVID-19." (PMID 35264675, 2022). "The IL17A/IL17F gene region, which had the lowest P value in the GWAS comparing severe and mild COVID-19 patients in Japanese, met the genome-wide significance level as a result of an integrated analysis with the international meta-GWAS." (PMID 35264675, 2022). "Meanwhile, the patient with myopericarditis after COVID-19 vaccination showed a slightly increased level of Th17-type cytokines including IL-17A, IL-17F, and IL-22 compared to healthy controls, but they were lower than those of recently vaccinated controls." (PMID 35251049, 2022). "Severe COVID-19 patients displayed reduced levels of IL-12p70, whereas the levels of IL-17A and IL-17F were lower in both mild and severe COVID-19 patients, compared to healthy donors." (PMID 33692788, 2021). "IL17-A and IL17-F are increased in COVID-19 patients [TE90], and genes related to IL17 signalling are significantly enriched in the severe-fatal group [TE96]." (PMID 34876157, 2021). "Considering the results demonstrating that in severe COVID-19, IL-17F levels are increased, we investigated whether IL-17F alone was sufficient to activate endothelial cells in vitro and mediate neutrophil adhesion." (PMID 39493750, 2024). "Except for IL-8 decreased in the second trimester after infected with SARS-CoV-2, IL-2, TNF-α, TNF-β, IFN-γ, IL-4, IL-5, IL-6, IL-10, IL-17A, IL-17F, IL-22, IL-1β and IL-12p70 didn't change in the three trimesters between healthy pregnancies and pregnant women with COVID-19." (PMID 39113896, 2024). "Moreover, increased plasma levels of IL-17D, IL-17E and IL-17F were noted when comparing severe versus mild COVID-19." (PMID 39493750, 2024). "Th17 cells during COVID-19 are characterized by phenotype typical to tissue resident memory T cells also expressing the genes associated with cytolytic potential (SRGN, GZMB, and GNLY) and cytokine genes encoding IL-21, IL-17F, IL-17A, IFN-γ, and GM-CSF." (PMID 37626620, 2023). "Our findings revealed that the IL-17F H161R variant does not influence the risk of COVID-19 in the studied population." (PMID 36349054, 2022). "If the measurement of serum IL17F levels confirms a decrease in IL17F levels in severe COVID-19 patients, it is expected to be an effective and important serum marker for predicting the severity of COVID-19." (PMID 35264675, 2022).